ZNF615 (zinc finger protein 615)
Description:
May be involved in transcriptional regulation.
Synonyms: FLJ33710
Tractability: PROTAC: ubiquitination databases record sites on it.
Gene: Protein-coding gene on chromosome 19 (51,991,332 to 52,008,230, reverse strand). Ensembl gene ENSG00000197619.
Subcellular location: Nucleus
Subcellular location (Human Protein Atlas): Mitochondria; Nucleoli
Pathways (Reactome):
Gene expression (Transcription): Generic Transcription Pathway
Gene Ontology:
Molecular function: transcription cis-regulatory region binding
Biological process: regulation of transcription by RNA polymerase II; regulation of DNA-templated transcription
Cellular component: nucleus
Genetic constraint (gnomAD): Loss-of-function variants: 11 observed, 13.3 expected, observed/expected ratio (o/e) 0.83, 90% interval 0.52 to 1.37. The upper end of that interval is the gene's LOEUF score, 1.37, which puts it in group 5 of 6, group 1 being the genes least tolerant of losing a copy. Missense variants: 829 observed, 930.81 expected, observed/expected ratio (o/e) 0.89, 90% interval 0.84 to 0.94. Synonymous variants: 259 observed, 306.48 expected, observed/expected ratio (o/e) 0.85, 90% interval 0.76 to 0.94.
Homologues: Orthologues: chimpanzee ZNF615 (98% identical), macaque ZNF615 (95% identical), dog ZNF615 (83% identical). Paralogues in human: ZNF432 (55% identical), ZNF268 (42% identical), ZNF33B (37% identical), RBAK (36% identical), ZNF182 (36% identical), ZNF841 (36% identical), ZNF484 (36% identical), ZNF605 (36% identical), ZNF33A (35% identical), ZNF658 (35% identical), ZNF717 (35% identical), ZNF229 (35% identical), and 164 more.
Diseases named in the same sentence as ZNF615 in open-access papers:
ZNF615 is named in the same sentence as 2 diseases in open-access papers, as found by Europe PMC text mining. Sharing a sentence is not in itself a finding about the gene and the disease. The quoted sentences say what the papers report.
cancer (1 paper, 2022). A tumor composed of atypical neoplastic, often pleomorphic cells that invade other tissues. "Several genes from the zinc finger family, including ZNF577, ZNF649, ZNF615, ZNF614, and ZNF432, are under intense investigation due to their altered methylation status in various cancer types." (PMID 36553064, 2022).
ZNF615 also shares sentences with these, for which no sentence is quoted: autism (1 paper).